MMP10 (matrix metallopeptidase 10)
Diseases named in the same sentence as MMP10 in open-access papers (continued):
Sharing a sentence is not in itself a finding about the gene and the disease.
diabetes (14 papers, 2011 to 2025). "Other associations found in this study, such as MMP-10 with age and diabetes and MMP-2 with age, hypertension and 90-days mortality, were only significant in VdH possibly explained by larger sample size and statistical power of this cohort." (PMID 32587306, 2020). "Notably, MMP-10 was significantly associated with MACE in PAD patients with diabetes, while MMP-7 showed an association in female PAD patients, underscoring their relevance in specific high-risk subgroups." (PMID 40563493, 2025). "In the kidneys of patients with diabetes, MMP10 contributed to the inflammatory macrophage response, which was ameliorated by MMP10 knockout." (PMID 39910908, 2025). "To conclude, we found that serum 25(OH)D3 concentration was significantly inversely associated with MMP-10 and TIMP-1 levels in patients with diabetes." (PMID 36079742, 2022). "Third, subgroup analyses revealed that MMP-10 was predictive of 2-year MACE in PAD patients with diabetes, while MMP-7 was predictive in female PAD patients, suggesting these proteins may serve as prognostic markers for specific high-risk subgroups." (PMID 40563493, 2025). "Elevated MMP-10 levels are found in various chronic inflammatory conditions and might play a particularly important role in diabetes as an early marker of developing microvascular complications." (PMID 36079742, 2022). "Interestingly, diabetes-related alterations of the extracellular matrix and adhesion molecules were varied; Pecam, Mmp10, Lamc1, Itgb7, Mmp9, and Timp4 were up-regulated, but Col11a1, Fn1, Admts2, and Itgav were down-regulated." (PMID 21984919, 2011). "After adjusting for baseline factors—including age, sex, dyslipidemia, hypertension, smoking status, diabetes, CHF, CAD, and prior stroke—plasma levels of MMP-10 and MMP-7 remained independently correlated with 2-year MACE in PAD patients." (PMID 40563493, 2025). "MMP-10 and TIMP-1 were significantly higher (p = 0.02 for MMP-10 and p < 0.001 for TIMP-1) in patients with diabetes compared to controls, after adjusting for age, gender and BMI." (PMID 31913319, 2020). "Increased serum levels of MMP-10 and TIMP-1 were found in patients with diabetes compared to healthy subjects." (PMID 31913319, 2020). "Proliferative retinopathy (n = 146) was associated with higher levels of MMP-2 [0.71 (0.45; 0.96)], MMP-3 [0.49 (0.28; 0.70)], MMP-10 [0.39 (0.11; 0.66)] and TIMP-1 [0.54 (0.28; 0.81)] after adjustment for age, sex, duration of diabetes and HbA1c (Model 1)." (PMID 25848912, 2015). "This study demonstrates positive associations of CDCP-1, FGF-21, IL-8, IL-18, eotaxin/CCL11, MMP-10, TNFRSF9, CCL25 and IL-10RB with depressive symptoms in people with diabetes without interaction with diabetes type." (PMID 39799156, 2025). "The associations between MMP-1, MMP-9, MMP-10, and TIMP-1 with cfPWV did not materially change after adjustment for age instead of age and diabetes duration." (PMID 29070037, 2017). "Consistent with this view, in a streptozotocin (STZ)-induced murine diabetes model, absence of MMP-10 partially protects kidney from diabetes-induced renal injury, manifested by improved renal function, less expansion of the mesangial matrix, as well as reduced macrophage influx." (PMID 35216251, 2022). "Nine biomarkers were positively associated with depressive symptoms in the total sample (CCL11/eotaxin, CCL25, CDCP1, FGF-21, IL-8, IL-10RB, IL-18, MMP-10, TNFRSF9; all p < 0.05) without interaction by diabetes type." (PMID 39799156, 2025).
bladder cancer (12 papers, 2006 to 2025). "Univariate analysis indicated age, race, MMP9, IL8, VEGFA, CA9, PAI1, ApoE, A1AT, ANG and MMP10 were associated with bladder cancer." (PMID 33823873, 2021). "Given that we have recently demonstrated that MMP-10 expression at the RNA and protein level is increased in urine samples obtained from patients with bladder cancer, so there appears be a trend of association between malignancy and MMP-10." (PMID 24885595, 2014). "Only in the cases of MMP1 and MMP10 do the bladder cancer samples have lower marker concentrations than the control samples." (PMID 41228251, 2025). "Several of the individual genes upregulated by Gardnerella exposures are involved in epithelial to mesenchymal transition (Cxcl5, Cxcr2, Tff1) or known to be elevated during squamous metaplasia or bladder cancer (Anxa10, Fosl1, Krt6a, Mmp10)." (PMID 35782131, 2022). "The Western immunoblot test showed that the expression of both MMPs was similar for all investigated tissues except for MMP-10 in high-grade urinary bladder cancer." (PMID 34441979, 2021). "The tissue of low-grade of urinary bladder cancer was characterized by a significant increase in specific activity of MMP-10 (p < 0.001)." (PMID 34441979, 2021). "Both low-grade and high-grade urinary bladder cancers contain a four-times lower level of MMP-3 than MMP-10." (PMID 34441979, 2021). "That is why MMP-10 seems to be much more important and valuable in the course of urinary bladder cancer than MMP-3." (PMID 34441979, 2021). "The overexpression of MMP10 was associated with higher grade disease, while overexpression of MMP10, PAI1, SDC1 and ANG were associated with high stage bladder cancer and CA9 was associated with low stage bladder cancer." (PMID 31905599, 2019). "In this study, we evaluated MMP-10 expression through immunohistochemical staining of a commercial bladder cancer TMA (70 benign samples and 188 cancer samples)." (PMID 24885595, 2014). "We found that MMP-10 expression is positively correlated with an invasive phenotype in both human cervical and bladder cancers." (PMID 24885595, 2014). "Within this study, analysis of 188 tumor specimens confirmed that MMP-10 protein expression was increased in human bladder tumors, and, as in cervical cancer study, a correlation between more aggressive bladder cancers and MMP-10 expression was noted." (PMID 24885595, 2014). "Relative to control cases, a reduction in SDC1 and overexpression of MMP9, MMP10, SERPINE1, IL8, APOE, SERPINA1, ANG were associated with high stage bladder cancer." (PMID 25387487, 2014). "Here, we report that MMP-10 expression is positively correlated with the invasiveness of human cervical and bladder cancers." (PMID 24885595, 2014). "It has been demonstrated that MMP-10 expression is increased in several human tumors of epithelial origin, including gastric cancer, bladder cancer, esophageal cancer, skin cancer and non-small cell lung cancer (NSCLC)." (PMID 24885595, 2014). "Additionally, miR-370-3p impeded bladder cancer cell invasion by suppressing Wnt7a expression, thus inhibited classical Wnt/β-catenin signal transduction and matrix metalloproteinase 10 (MMP10) levels." (PMID 35962353, 2022). "Generally, obtained results demonstrated a contrary participation of MMP-3 and MMP-10 in ECM remodeling what may be crucial in the pathogenesis of human urinary bladder carcinoma." (PMID 34441979, 2021). "In low-grade urinary bladder cancer, the actual activity of MMP-10 was more than four times higher." (PMID 34441979, 2021). "Furthermore, demonstration of a correlation between MMP-10 expression and invasive cervical and bladder cancers supports a role for MMP-10 in human tumor progression." (PMID 24885595, 2014). "It would be interesting to investigate whether MMP-10 expression is correlated with disease prognosis in cervical and bladder cancers, as it has been in esophageal carcinoma, current studies to address this are underway." (PMID 24885595, 2014).
bladder cancer (continued). "The actual and specific activities vary in both grades of urinary bladder cancer; however, the highest activity for MMP-3 and MMP-10 was found in low-grade tissues." (PMID 34441979, 2021). "Similar, we report an increase of both MMP-10 and PAI-1 in voided urine samples from subjects with bladder cancer." (PMID 24885595, 2014). "The expression of seven of the 10 bladder cancer -associated diagnostic signature (MMP9, MMP10, PAI1, CA9, APOE, SDC1, and ANG) showed a positive association with bladder cancer diagnosis, while IL8 and A1AT showed a negative correlation with cancer diagnosis." (PMID 31905599, 2019). "Additionally, the expression of MMP-10 does not indicate any relationship with the progression of bladder carcinoma." (PMID 34441979, 2021). "However, the expression of MMP-10 likely does not show any relationship with the progression of urinary bladder cancer." (PMID 34441979, 2021).
dementia (11 papers, 2019 to 2025). Loss of intellectual abilities interfering with an individual's social and occupational functions. "Compared to the CU reference group, cognitive impairment at the MCI stage was associated with increased levels of TIMP-2 and TIMP-4, whereas the dementia stage was associated with increased levels of MMP-10 and TIMP-2." (PMID 37221606, 2023). "Studies of cerebrospinal fluid (CSF) and blood in dementia patients show upregulation of two potential biomarkers of inflammation at the cellular level, MMP10 and apoptosis-associated speck-like protein containing a CARD (ASC)." (PMID 36305000, 2022). "The up-regulation of MMP-10 has also been shown to be linked to some other neurological diseases, such as Alzheimer ‘s disease, dementia, and intracerebral hemorrhage." (PMID 37293545, 2023). "Post hoc comparisons revealed significantly higher MMP-10 levels in AD dementia patients (mean = 28.4 pg/mL) and MCI-AD patients (24.0 pg/mL) compared to CU A− (16.5 pg/mL, P < 0.01) and CU A+ controls (15.4 pg/mL, P < 0.01)." (PMID 37221606, 2023). "Since MMP10 is elevated in the central nervous system of dementia patients, the next step was to evaluate the consequences of ASC-specks mediated release of cMMP10 on microglia." (PMID 36305000, 2022). "More pertinent to this study, TREM2 protein levels correlate with MMP10 levels in patients with dementia." (PMID 36305000, 2022). "By means of multiplex bead-based immunoassays, MMP-10 has already been found to be increased in the CSF of AD patients compared to controls, as was its CSF/plasma ratio compared to other forms of dementia (namely, vascular dementia)." (PMID 34440700, 2021). "Finally, compared to the CU reference group MCI and dementia were associated with increased MMP-10 levels in women (MCI β = 0.22, P < 0.01 and dementia β = 0.37, P < 0.01)." (PMID 37221606, 2023). "For example, MMP9 and MMP10 are elevated in the CSF of patients with dementia." (PMID 36305000, 2022). "Elevated levels of MMP-10 have also been reported in other forms of dementia." (PMID 36031900, 2022). "Additionally, MMP-10 was found to be increased in the CSF of AD-dementia patients and patients with MCI and a CSF A+ profile compared to controls in a previous study based on the same multiplex testing and on a similar statistical approach." (PMID 34440700, 2021). "Our study highlights the changes and potential contributions of several chemokines (CXCL1, CCL3, CXCL5, CXCL6, CCL3, CCL19), interleukins (IL8, IL6-RA, IL18-BP), and other immune markers (OSM, ALCAM, OPG, CHIT1, YKL-40, STAMBP, MMP-9, MMP-10) in the prodromal and dementia phases of AD." (PMID 31694701, 2019). "This is in line with recent findings reporting that higher MMP-10 levels are associated with increased risk of conversion from MCI to AD dementia, and highlights that MMP-10 levels may also provide prognostic information for patients at the dementia stage." (PMID 37221606, 2023). "For example, elevated levels of MMP-2, MMP-3, MMP-10, TIMP-1, and TIMP-2 were detected in the CSF of patients with delirium who had pre-existing dementia." (PMID 40507855, 2025). "Nineteen proteins (20%) were dysregulated in FTD and AD compared to controls, which likely represent general dementia processes (e.g., CHIT1, MMP10, and MMP12)." (PMID 40866991, 2025). "Recently, we found that both MMP10 and the assembled inflammasome complex ASC-specks are elevated in the CSF of dementia patients." (PMID 36305000, 2022).
pancreatic cancer (10 papers, 2010 to 2025). "Of these, the expression of several matrix metalloproteinases was decreased, including Mmp10, Mmp12, and Mmp13; these metalloproteinases have been implicated in epithelial-to-mesenchymal transition, invasion, and metastases in pancreatic cancer." (PMID 41373844, 2025). "Mechanistically, we find that soluble molecules released by hypoxia-activated stromal cells contribute to the invasive growth of pancreatic cancer cells and that among these, MMP10 is likely to be the major driving factor of invasive growth." (PMID 33105540, 2020). "YY1 suppresses invasion and metastasis of pancreatic cancer cells by downregulating MMP10 in a MUC4/ErbB2/p38/MEF2C-dependent mechanism." (PMID 24884523, 2014). "The YY1 high-level overexpression suppresses invasion and metastasis of pancreatic cancer cells by downregulating MMP10 via a MUC4/ErbB2/p38/MEF2C-dependent mechanism." (PMID 24884523, 2014). "We also explored the potential mechanisms underlying the tumor suppression role of YY1 and found that YY1 suppresses invasion and metastasis of pancreatic cancer cells by downregulating MMP10 in a MUC4/ErbB2/p38/MEF2C-dependent mechanism." (PMID 24884523, 2014). "Recently, MMP-10 was shown to be specifically upregulated and involved in metastatic spread to the liver in xenografts of pancreatic cancer." (PMID 20553613, 2010). "A report indicated that YY1 could suppress invasion and metastasis by downregulating MMP10 in a MUC4/ErbB2/p38/MEF2C-dependent manner in pancreatic cancer cells, suggesting MEF2C phosphorylation is required for MMP10 expression." (PMID 30836712, 2019). "Gene expression profiling revealed that Mmp10 is commonly overexpressed in many forms of human cancer, including lung, head and neck, esophageal, bladder, skin, colorectal, breast, cervical, nasopharyngeal, tongue and pancreatic cancers, suggesting a widespread role for Mmp10 in human malignancy." (PMID 22022614, 2011). "For example, YY1 suppresses cell invasion and metastasis by downregulating MMP10 expression and increases apoptosis through BAX activation in pancreatic cancer cells, suggesting that YY1 functions as a tumor suppressor." (PMID 28412749, 2017).
colorectal cancer (9 papers, 2012 to 2025). A primary or metastatic malignant neoplasm that affects the colon or rectum. "In colorectal cancer, MMP10 is up-regulated in cancerous tissue and adversely associated with patients survival." (PMID 29933410, 2018). "We observed similar associations between Mmp10 expression and metastatic behavior of human colorectal cancer, melanoma, breast, renal and prostate cancers." (PMID 22545096, 2012). "This study also underscores the significant diagnostic capabilities of MMP10 and MMP3 in colorectal cancer." (PMID 40595862, 2025). "Upregulation of several MMPs including MMP7, MMP10 and MMP12 in cancerous tissue and adverse association with survival has been evaluated likewise in colorectal cancer." (PMID 27431388, 2016). "Consistently with MMP7 and MMP10 also overexpression of MMP12 in colorectal cancer specimen is reported." (PMID 27431388, 2016). "A study examining the host transcriptome and microbiota composition of colorectal cancer tumors found high expression of MMP10 in tumor tissues and a significant increase in the genus Bacteroides, indicating a link between the host gene MMP10 and the genus Bacteroides." (PMID 38557130, 2024). "As for MMP7 for MMP10 overexpression in colorectal cancer specimen is described." (PMID 27431388, 2016). "Furthermore, we recapitulated the gene expression levels of Mmp3, Mmp10, and Mmp13 from large cohorts of ulcerative colitis (UC) and colorectal cancer (CRC) patients that are available from the GEO database (GSE38713 and GSE37364)." (PMID 25742789, 2015).
Alzheimer disease (8 papers, 2018 to 2026). A progressive, neurodegenerative disease characterized by loss of function and death of nerve cells in several areas of the brain leading to loss of cognitive function such as memory and language. "Several SASP factors, including IL-6, IL-1β, TNF-α, MMP-1, MMP-3, and MMP-10, have also been found to be elevated in the cerebrospinal fluid and serum of patients with Alzheimer’s disease." (PMID 37569663, 2023). "MMP-10 is increased in CSF of patients with Alzheimer’s disease and MMP-3 is elevated in mixed dementia (unpublished data)." (PMID 30533010, 2018). "Mendelian randomization analyses suggested causal roles for several proteins, for example, ApoE, CD33, and GRN in Alzheimer's disease, MMP‐10 in preclinical Alzheimer's disease, SIGLEC9 in amyotrophic lateral sclerosis, and CD38, GPNMB, and ADAM15 in Parkinson's disease." (PMID 36504281, 2023). "Two of the studied proteins, MMP-10 and TIMP-2, differed between the patients with Alzheimer’s disease and the controls." (PMID 37221606, 2023). "CSF levels of GRN, MMP‐10, and GPNMB were altered in Alzheimer's disease, preclinical Alzheimer's disease, and Parkinson's disease, respectively." (PMID 36504281, 2023).
asthma (8 papers, 2013 to 2024). "In our study, MMP10 was one of few proteins associated only to lean asthma." (PMID 36973952, 2023). "Although the roles of MMP-7 and MMP-10 in asthma are still being elucidated, MMP-9 has shown consistent associations with disease severity and airway remodeling processes." (PMID 38275403, 2024). "MMP-7, MMP-9, and MMP-10 are important in asthma, particularly in airway remodeling and extracellular matrix alterations." (PMID 38275403, 2024). "MMP10 has been related to airway remodelling and bronchial inflammation in asthma and regulates macrophage activity and subsequently the extent of inflammatory injury on the airways." (PMID 36973952, 2023). "Taken together, TNF-α is involved in the pathogenesis of asthma, possibly through leading to increased MMP10 expression, thereby promoting wnt/β-catenin signaling." (PMID 35000533, 2022). "TXL can be a promising drug for the treatment of asthma due to its inhibition of MMP10 expression by blocking Wnt/β-catenin pathway." (PMID 35000533, 2022). "Interestingly, experiments with both two types of cell lines led to the conclusion that MMP10 may activate canonical Wnt signaling by inhibiting Wnt5a, which led to our further prediction that MMP10 might be also associated with Wnt/β-catenin in asthma." (PMID 35000533, 2022). "In asthma biopsy, the expressions of MMP10 and MET were increased in bronchial epithelial cells, subepithelial inflammatory cells and resident cells." (PMID 35000533, 2022). "TXL is able to suppress inflammation and apoptosis induced by TNF-α through suppressing MMP10, suggesting the potential effect of TXL against asthma." (PMID 35000533, 2022). "Interestingly MMP10 and ADAM19 gene expression has also been shown to be upregulated in pBECs from subjects with asthma." (PMID 23384071, 2013). "A key observation in our study was that MMP-7, MMP-9, and MMP-10 concentrations remained similar across all the investigated groups, indicating that they may not possess any prognostic value in asthma." (PMID 38275403, 2024).